HHLA2 (HHLA2 member of B7 family)
Diseases named in the same sentence as HHLA2 in open-access papers (continued):
Sharing a sentence is not in itself a finding about the gene and the disease.
cervical adenocarcinoma (1 paper, 2024). An adenocarcinoma arising from the cervical epithelium. "In a group of 76 patients suffering from cervical adenocarcinoma (AC), HHLA2 expression was observed in 97.4% of tumor samples, and 81.6% of them exhibited high HHLA2 expression." (PMID 38786018, 2024).
chronic myeloid leukemia (1 paper, 2024). "Additionally, studies have reported that HHLA2 in chronic myeloid leukemia cells interacts with KIR3DL3 in NK cells (inhibitory receptor for HHLA2), leading to the inhibition of NK cell cytotoxicity." (PMID 38951802, 2024).
colorectal tumors (1 paper, 2019). "It was found that the expression of HHLA2 was significantly elevated in renal tumors, and significantly decreased in colorectal tumors." (PMID 31379814, 2019).
dysplasia (1 paper, 2019). A usually neoplastic transformation of the cell, associated with altered architectural tissue patterns. "After comparing the HHLA2 and TMIGD2 expression levels in OSCC, dysplasia, and mucosa, we found increased HHLA2 expression in OSCC and dysplasia, while the TMIGD2 expression was decreased in OSCC and dysplasia." (PMID 31089395, 2019).
esophageal squamous cell carcinoma (1 paper, 2024). Esophageal squamous cell carcinoma (ESCC) is a type of esophageal carcinoma (EC) that can affect any part of the esophagus, but is usually located in the upper or middle third. "A few authors tackled the issue of HHLA2 expression in oral (OSCC) and esophageal squamous cell carcinoma (ESCC)." (PMID 38786018, 2024).
gastrointestinal stromal tumor (1 paper, 2025). "Adenocarcinomas (n = 15) demonstrated reduced or absent expression, and no expression was found in neuroendocrine (n = 2), pseudopapillary (n = 1) or gastrointestinal stromal tumor (n = 1) subtypes, whereas adjacent normal ducts showed high HHLA2 positivity." (PMID 40255615, 2025).
hepatic (1 paper, 2025). "HHLA2 overexpression significantly increased hepatic tumor load in these mice." (PMID 40394703, 2025).
kidney tumors (1 paper, 2023). "We show that HHLA2 is expressed on primary kidney tumor cells ex vivo by flow cytometry and mRNA expression." (PMID 37891555, 2023). "Analysis of HHLA2 expression revealed that HHLA2 is expressed on tumor cells in primary kidney tumors ex vivo; however, its expression gradually diminishes during a 4-week in vitro culture period." (PMID 37891555, 2023). "Flow cytometry and quantitative real-time PCR were used to analyze HHLA2 expression in primary kidney tumors ex vivo and during in vitro culture." (PMID 37891555, 2023).
leukemia (1 paper, 2024). A malignant (clonal) hematologic disorder, involving hematopoietic stem cells and characterized by the presence of primitive or atypical myeloid or lymphoid cells in the bone marrow and the blood. "Moreover, HHLA2 expression was undetectable in leukemia cells from BM of both mouse groups treated with 17C7 and B5B5." (PMID 38167704, 2024). "Loss of TMIGD2, but not HHLA2, led to significant inhibition of leukemia cell growth over the course of 6 days." (PMID 38167704, 2024). "To further evaluate the functions of TMIGD2 and HHLA2 in leukemia cells, we next performed small hairpin RNA (shRNA)-mediated knockdown of TMIGD2 (shTMIGD2) or HHLA2 (shHHLA2) in Kasumi-1, HEL and K562 cell lines." (PMID 38167704, 2024).
medullary thyroid carcinoma (1 paper, 2024). "Similarly, the expression of HHLA2 was observed in medullary thyroid carcinoma (MTC) tissues but not in normal tissues." (PMID 38786018, 2024).
myeloma (1 paper, 2021). "Other B7 co-inhibitory ligands, such as CD86, CD80, and HHLA2, showed high expression levels in myeloma cell lines relative to the other cancer cell lines, implying that these B7 ligands might serve as potential targets for immune checkpoint therapy." (PMID 34504297, 2021).
sarcoma (1 paper, 2022). A usually aggressive malignant neoplasm of the soft tissue or bone. "Paradoxically, high HHLA2 expression in ICC was associated with low TIL infiltration, and there was no clear association in sarcomas." (PMID 36003385, 2022).
skin cutaneous melanoma (1 paper, 2022). "Further comprehensive analysis from TCGA database demonstrated that the highly expressed HHLA2 was remarkably correlated with better prognosis, high infiltration status of various immune-active cells and immune activated pathways in skin cutaneous melanoma (SKCM)." (PMID 36003385, 2022).
cancer (80 papers, 2016 to 2025). A tumor composed of atypical neoplastic, often pleomorphic cells that invade other tissues. "Human endogenous retrovirus-H long terminal repeat-associating 2 (HHLA2), a member of the B7 family, is widely expressed across human cancers and is emerging as a promising immune checkpoint target for therapeutic development." (PMID 40255615, 2025). "HHLA2, a B7 family ligand, is highly expressed in various cancers, is associated with immune evasion, and has a bi-directional regulatory effect on T cells." (PMID 39234566, 2024). "Human endogenous retrovirus subfamily H long terminal repeat associating protein 2, (HHLA2), a member of B7 family, exhibits heightened expression in various malignant tumors." (PMID 38762741, 2024). "Human endogenous retroviral H long terminal repeat sequence-associated protein 2 (HHLA2), a member of the B7 family, is highly expressed in many cancers." (PMID 37865763, 2023). "It was also attested a positive association between HHLA2 with increased density of CD8+ T cells in this cancer type." (PMID 38144305, 2023). "High HHLA2 overexpression in cancer tissues has been linked to cancer development and malignant characteristics, whereas HHLA2 deficiency inhibits NSCLC cell proliferation, migration, and M2 macrophage polarization." (PMID 35371079, 2022). "HHLA2 expression in pan-cancer and the association with prognosis and immune microenvironment were identified by analyzing gene expression profiles from TCGA database with selected bioinformatics tools and methods." (PMID 36003385, 2022). "We have previously reported that as a novel therapeutic target, HHLA2 is overexpressed in human ccRCC tissues, and its expression is significantly associated with the prognosis and cancer progression of the patients." (PMID 35794583, 2022). "BATF (Basic Leucine Zipper ATF-Like Transcription Factor) affects the prognosis of many kinds of cancer by combining with HHLA2 (HERV-H LTR-associating 2) DNA, especially the prognosis of KIRC." (PMID 35832648, 2022). "This study is a follow up from a previously published work on expression patterns of MAGEB5 and HHLA2 transcripts across viral and cancer associated samples, whose genetic co-expression patterns suggests viral disease and cancer causation." (PMID 34320928, 2021). "But in TNBC, overexpressed HHLA2 was linked to advanced stage of cancer at diagnosis, and also was linked to a high recurrence risk." (PMID 34181347, 2021). "In the combined cohort high tumoural HHLA2 expression levels were significantly associated with delayed cancer recurrence and improved post-operative cancer-specific survival." (PMID 32071413, 2020). "First, we demonstrate that higher HHLA2 expression is not only associated with prolonged survival, but also with delayed cancer recurrence." (PMID 32071413, 2020). "Higher HHLA2 expression in cancer cells was significantly associated with improved post-operative cancer-specific survival." (PMID 32071413, 2020). "Several studies have shown that higher expression of HHLA2 in human cancer tissues is significantly associated with cancer progression and poor prognoses of the patients." (PMID 31015801, 2019). "Higher t-HHLA2 was associated with longer cancer-specific and progression-free survival." (PMID 36598731, 2023). "This discrepancy may partially be caused by the fact that we focused on cancer cell expression while HHLA2 is also expressed in the tumour microenvironment such as immune cells, stromal cells and neural tissue." (PMID 32071413, 2020). "Likewise, increased HHLA2 expression in cancer cells was positively associated with delayed cancer recurrence." (PMID 32071413, 2020).
cancer (continued). "In univariate analysis, HHLA2 expression, T-stage, tumour differentiation grade, margin status, lymph node status, CA-19.9 level and tumour location (ampulla versus pancreas) were significantly associated with cancer-specific survival." (PMID 32071413, 2020). "Moreover, by comparing three HHLA2 expression level categories (absent, low, high expression) instead of two categories, we show that increases in HHLA2 expression are associated with prolonged time to recurrence and cancer-specific death in a dose-dependent fashion." (PMID 32071413, 2020). "To investigate if HHLA2 predicts c-Met inhibitor response, we analyzed data from the Cancer Cell Line Encyclopedia (CCLE)." (PMID 40394703, 2025). "The development of bispecific antibodies targeting both PD-L1 and HHLA2 signaling has the potential to stimulate the immunogenic pathway and enhance responses to ICIs, making it a promising approach in cancer immunotherapy." (PMID 40255615, 2025). "By integrating these findings, it becomes evident that the HHLA2-TMIGD2 pathway plays a crucial role in cancer progression and immune regulation, offering prospects for future research and therapeutic development." (PMID 40255615, 2025). "High HHLA2 expression was observed in 31.4% of patients with MTC and was significantly linked to lymph node metastasis and advanced cancer stages." (PMID 40255615, 2025). "First, differences in study populations, such as patient demographics (age and sex), cancer type and stage, can influence HHLA2 expression and its prognostic implications." (PMID 40255615, 2025). "To explore the underlying mechanisms of HHLA2-mediated HCC progression, we analyzed RNA-sequencing data from TCGA and protein expression data from The Cancer Proteome Atlas (TCPA)." (PMID 40394703, 2025). "The association of stromal HHLA2 with poorer prognosis suggests that the tumor-supportive stroma can influence the overall impact of HHLA2 on cancer progression." (PMID 40255615, 2025). "HHLA2 exhibits broad expression in patients with PD-L1-negative cancers, making it a valuable target for immunotherapy alongside PD-L1." (PMID 40255615, 2025). "Search strategies combined MeSH terms and keywords related to ‘HHLA2’, ‘B7-H7’, ‘B7y’, ‘B7-H5’ and ‘cancer’, with a specific focus on endocrine-related cancers." (PMID 40255615, 2025). "Through these interactions, HHLA2 can deliver either stimulatory or inhibitory signals, respectively, thereby affecting the immune system’s ability to detect and target cancer cells." (PMID 40255615, 2025). "Previously, only one receptor for HHLA2 was known, which is why contradictory studies proved the co-stimulatory or co-inhibitory role of this molecule in cancer development." (PMID 38786018, 2024). "The expression levels of HHLA2 were found to be correlated positively with tumor invasion of adjacent structures, poor tumor differentiation, and advanced Barcelona Clinic Liver Cancer (BCLC) classification stage in HCC." (PMID 38786018, 2024). "HHLA2 is a checkpoint from the B7 family that can play a co-stimulatory or co-inhibitory role in cancer, depending on the binding receptor." (PMID 38731979, 2024). "Studies indicate that regulating this molecule’s expression in cancer cells differs from HHLA2 pathways in monocytes." (PMID 38786018, 2024). "Mechanistically, LINC00665 was found to recruit the transcription factor TCF7, known for its involvement in cancer-related signaling pathways, to promote the transcription of HHLA2." (PMID 38951802, 2024). "The intensity of HHLA2 staining was visibly stronger and revealed HHLA2 localization on the cytoplasm and membrane of cancer cells and in the stromal fibroblasts." (PMID 38786018, 2024). "According to many researchers, HHLA2 seems to be a promising target for immunotherapies in the cancers resistant to any PD-L1 therapies." (PMID 38786018, 2024). "In total, 77% of tumors were positive for HHLA2, and HHLA2 mRNA was detected in all 23 examined cancer tissues." (PMID 38786018, 2024).
cancer (continued). "The evolving landscape of HHLA2 research deepens our understanding of its immunomodulatory functions and offers new opportunities for employing its therapeutic potential in cancer treatment." (PMID 38731979, 2024). "Additionally, it was reported in previous studies that HHLA2 may exhibit both protumor and antitumor activity depending on tumor type, which suggests a more complicated association between HHLA2 expression and prognosis in different cancers." (PMID 38731979, 2024). "Furthermore, the interaction between HHLA2 and its receptors has been implicated in regulating immune cell functions beyond T cells, including the modulation of dendritic cell activity and cytokine production, suggesting broader implications for immune regulation in cancer." (PMID 38731979, 2024). "HHLA2 can be a prognostic biomarker in various cancers, such as ovarian and pan-cancer (all cancers)." (PMID 38835341, 2024). "The expression of HHLA2 occurs primarily in carcinomas of the breast, lung, thyroid, ovary, pancreas, liver, and gastrointestinal tracts; the localization of the protein is both membranous and cytoplasmic in tumor cells." (PMID 38786018, 2024). "GSEA and GO showed that HHLA2 upregulation correlated with cancer-related pathways and several biological functions." (PMID 36982953, 2023). "On the other hand, HHLA2 protein is overexpressed in many types of human cancers, including kidney, breast, lung, thyroid, melanoma, pancreatic, ovarian, liver, bladder, colon, prostate, and esophageal cancer." (PMID 37891555, 2023). "We evaluated the immunohistochemical expression of HHLA2 and fibroblast activation protein (FAP), which is a marker of cancer-associated fibroblasts, in UTUC tissues from 85 patients who underwent nephroureterectomy." (PMID 36598731, 2023). "In this study, we observed that the elevated expression of t-HHLA2 was related to a lower histological grade of cancer and longer CSS and PFS." (PMID 36598731, 2023). "Of note, like other important B7 family ligands, HHLA2 has been found to be overexpressed in lots of human cancers, and it can be used as a useful biomarker for the prediction of cancer progression and postoperative prognosis of the patients." (PMID 35794583, 2022). "High intratumoral HHLA2 expression is often an adverse predictor of survival in individuals with different cancer types, such as triple-negative breast cancer and renal cell carcinoma, where it is related to increased cancer recurrence or decreased survival." (PMID 36499340, 2022). "We next explored how HHLA2 links to the biological activities of cancer initiation and how it impacts immunological features." (PMID 35371079, 2022). "HHLA2 is a newly discovered molecule to ubiquitously and highly expressed in many cancers and belongs to the B7 family." (PMID 36003385, 2022). "The GSEA enrichment analysis was conducted to uncover the biological behavior behind HHLA2 expression pattern, and the result suggested that HHLA2 was engaged in the regulation of multiple immune-related cancer biological processes." (PMID 36003385, 2022). "HHLA2 was found to be ubiquitously expressed in pan-cancer with high level and correlate with the prognosis of patients." (PMID 36003385, 2022). "There were also contradictory results between HHLA2 expression and immune cell infiltration in different cancers." (PMID 36003385, 2022). "Priming and activation (step 3), infiltration of immune cells into tumors (step 5), and detection and killing of cancer cells by T cells (step 7) were all reduced in the HHLA2-high group in the TCGA cohort." (PMID 35371079, 2022). "We have previously reported that HHLA2 was highly expressed in human ccRCC tissues, and potentially involved in the promotion of cancer progression." (PMID 35794583, 2022). "An increasing number of studies have demonstrated HHLA2 as a new immune checkpoint molecule and prognostic biomarker in cancers, especially in PD-1-negative human tumors." (PMID 35237510, 2022).